RNU2-45P (RNA, U2 small nuclear 45, pseudogene)
Gene: Small nuclear RNA gene on chromosome 6 (28,410,270 to 28,410,456, forward strand). Ensembl gene ENSG00000251877.
Homologues: Orthologues: rabbit U2 (34% identical), rat LOC120093491 (32% identical), pig U2 (30% identical), rat LOC120100443 (26% identical). Paralogues in human: U2 (50% identical), RNU2-43P (49% identical), RNU2-48P (49% identical), RNU2-4P (49% identical), RNU2-6P (49% identical), RNU2-52P (48% identical), RNU2-3P (48% identical), RNU2-56P (48% identical), RNU2-59P (48% identical), RNU2-8P (48% identical), RNU2-2 (47% identical), RNU2-32P (47% identical), and 65 more.